STAT1 (signal transducer and activator of transcription 1)
Diseases named in the same sentence as STAT1 in open-access papers (continued):
Sharing a sentence is not in itself a finding about the gene and the disease.
tumor (continued). "In addition, we also observed in our in vitro study that a STAT3 inhibitor increased CXCL9 expression in tumor cells, indicating the balance of p-STAT1/p-STAT3 was a determinant in regulating chemokine production in tumor cells." (PMID 35925680, 2022). "Loss of YTHDF1 mediated overexpression of interferon (IFN)-γ receptor 1 (IFNGR1) and JAK/STAT1 signaling pathway in tumor cells, which might contribute to restored sensitivity to anti-tumor immunity." (PMID 35193930, 2022). "Activated microglia assume the M1 phenotype characterized by the expression of STAT1 and are capable of stimulating antitumor immune responses by presenting antigens to adaptive immune cells, producing proinflammatory cytokines, and phagocytosing tumor cells." (PMID 35729639, 2022). "In addition, weaker, but significant correlations of nuclear and cytoplasmic STAT1 in the tumor cells and of STAT1-positive immune cells were observed with the CD20- and CD68-positive immune cell infiltrate." (PMID 35267462, 2022). "Based on these data, STAT3 may also play a tumor suppressor role and promote different functions depending on the tumor stage described for STAT1." (PMID 35207527, 2022). "Furthermore, we were able to show that PD-L1 and STAT1 expression correlated in both the tumor cells and the tumor infiltrating immune cells." (PMID 35267462, 2022). "STAT-1 was found to be involved in tumor aggressiveness and could be possibly implied in tumor resistance and immune system escape seen in cachectic patients." (PMID 36078078, 2022). "Furthermore, we evaluated STAT1 protein expression by western blotting and observed higher expression in the non-tumor tissues than in OS tissues." (PMID 33391546, 2021). "Most data suggest that activated STAT1 plays a function in cancer cells as a tumor suppressor." (PMID 33986802, 2021). "Furthermore, silencing of Stat1 expression inhibits tumor cell growth and sensitizes cancer cells to drug-induced apoptosis." (PMID 34685622, 2021). "Especially in the PCa early stages, STAT1 is assumed to function as a tumor suppressor." (PMID 34638338, 2021). "As there is only one tumor with somatic STAT1 mutation in pSKCM, we do not have the power to determine the relationship between STAT1 mutation and M1 macrophage abundance." (PMID 33619278, 2021). "As a tumor suppressor gene, STAT1 could inhibit the growth of HCC and induce cell arrest at G0/G1 phase." (PMID 34178664, 2021). "Based on this, one would speculate that downstream of IFN-α/β and IFN-γ, activation of STATs (particularly, STAT1) would exert a similar anti-tumor role." (PMID 34830176, 2021). "Moreover, Oct4 promotes tumor growth, whereas silencing of Stat1 expression reduces tumor growth in vivo." (PMID 34685622, 2021). "In this regard, a reciprocal regulation between STAT3 and STAT1 in tumor cells has been discussed and that different upstream signals (IFN-β vs. oncostatin-M) or even the IFN-βs from different cells may have opposite effects in response to RT and IOs." (PMID 34830176, 2021). "In particular, STAT1 plays a key role in cell growth and apoptosis, as it acts as a tumor suppressor by altering the function of protein, DNA, or RNA, or by inducing lipid peroxidation leading to tumor growth inhibition." (PMID 33917013, 2021). "RT-induced DSBs and subsequent ATM/ATR/CHK1 kinase activities have also been implicated in upregulation of tumor PD-L1 expression through direct STAT1/3-IRF1 activation, independent of neoantigen production." (PMID 34631532, 2021). "Existing evidence reveals that STAT1 has both tumor-suppressing and tumor-promoting functions involved in angiogenesis, cell proliferation, migration, invasion, apoptosis, drug resistance, stemness, and immune responses mainly through interacting and regulating target genes at multiple levels." (PMID 33834023, 2021).
tumor (continued). "By the protein–protein interaction between PAFR and FAK and FAK and the Signal Transducers and Activators of Transcription (STAT1), the receptor promoted tumor progression and contributed to early malignant transformation of BRCA1-mutant ovarian epithelial cells." (PMID 34571986, 2021). "Furthermore, Oct4 promoted Stat1 expression and tumor growth, whereas silencing of Stat1 reduced Oct4-induced tumor growth in human lung tumor xenograft models." (PMID 34685622, 2021). "Previous studies indicated that STAT1 was a double-edged sword in tumor progression." (PMID 34873163, 2021). "Moreover, IFN-γ production was low in both normal and tumor tissue and STAT1 and STAT3 were downregulated in tumor versus normal tissue." (PMID 33846436, 2021). "In summary, proteasome might degrade STAT1 at baseline and thus tumor cells were unresponsive to IFN-γ stimulation." (PMID 34758826, 2021). "For instance, STAT1 functions as a tumor suppressor through multiple mechanisms prevention of inflammation through modulation of the microbiota may provide another facet of its barrier to tumorigenesis." (PMID 34378531, 2021). "Additionally, MEK inhibitors have been reported to activate STAT1 signaling in mammary tumor cell line, inducing tumor immunogenicity through MHC-I and PD-L1 expression." (PMID 34322780, 2021). "STAT1 has a well-defined role as being a tumor suppressor for different cancers." (PMID 34622927, 2021). "In melanocytes, the agents that inhibit eukaryotic cell initiation factor 4A could downregulate the transcription level of STAT1 and indirectly downregulate PD‐L1 expression to induce tumor regression." (PMID 34382349, 2021). "Lastly, we examined the frequency of somatic copy number alterations (SCNA) associated with regulation of anti-tumor immune responses in pre-clinical and clinical studies: gains in MYC16, losses of PTEN17 and gains or losses in interferon pathway genes (PDCD1, STAT1, JAK1, and JAK2)." (PMID 34446728, 2021). "We identified STAT1 as a key gene for tumour microenvironment related to immune cells, which could be further studied in vitro and in vivo for clinical treatment with immunotherapy." (PMID 33608980, 2021). "Classically, IFN-γ inhibits the proliferation of tumor cells and promotes their apoptosis, as it can activate signal transducer and activator of transcription 1 (STAT1) through using the Janus kinase (JAK) signal transducer and activator of the transcription pathway." (PMID 35003090, 2021). "Moreover, we proved for the first time that LpCat1 directly interacted with STAT1 which was generally recognized as a tumor suppressor in HCC." (PMID 34178664, 2021). "Similarly, in our melanoma models, exogenously administered IL-33 activated mDCs in the TME, promoting cross-presentation of tumor antigen in a ST2/MyD88/STAT1-dependent fashion and restoring a competent anti-tumor T cell activity." (PMID 34209038, 2021). "ALDH1A3 and STAT1 mRNA levels were significantly upregulated in tumor samples." (PMID 34440089, 2021). "The broad spectrum of biological roles for STAT1 suggests that it might be difficult to target this factor specifically or selectively in tumor cells." (PMID 34572789, 2021). "As one homologue of STAT3, STAT1 usually functions as a tumour suppressor." (PMID 33546665, 2021). "Except for STAT1, the other seven genes were low expressed in tumor samples." (PMID 35127768, 2021). "In PCa and other tumor entities, STAT1 acts as a tumor suppressor and oncogene." (PMID 34638338, 2021). "Our further analyses revealed that there was positive feedback regulation between PKD3 and PD-L1, which could drive EMT of OSCC cells via the ERK/STAT1/3 pathway, thereby promoting tumour growth and metastasis." (PMID 33692335, 2021). "However, the collaboration between type I and type II IFN supports innate and adaptive anti-tumor immune responses, STAT1 protein plays an important role in the interconnection of these pathways." (PMID 34215720, 2021).
tumor (continued). "However, the prevalence of F4/80+ cells was 2.4-fold higher in WT AOM/DSS mice, compared to STAT1-/- AOM/DSS mice during advanced stages of tumor development (day 77)." (PMID 34299314, 2021). "In addition, we analyzed CD8, CD68, CD206, p-STAT1 and iNOS expression to evaluate alterations in tumor micro-environment and anti-tumor immune response due to treatment." (PMID 34282238, 2021). "We also identified STAT1 as a candidate transcription factor underlying gene expression differences in metastasis and non-metastasis tumor cells." (PMID 34026600, 2021). "To test this hypothesis, we analyzed alterations in macrophage accumulation during the course of the disease for 20-, 40-, and 77-day periods in STAT1-/- and WT mice, as an approximation of different stages of tumor progression." (PMID 34299314, 2021). "To test whether the mechanism behind the in vivo effects of EGCG was similar to that observed in vitro, we analyzed B16F10 tumor samples for STAT1 and IRF1 expression." (PMID 34832863, 2021). "In the tumor section excised at day 70 after tumor cell inoculation, Stat1 expression was higher in A549-Oct4 tumors than in A549-vector tumors, suggesting that Oct4 regulates Stat1 expression in vivo." (PMID 34685622, 2021). "Besides its involvement in antiviral and antibacterial response, STAT1 also induces growth inhibition and stimulation of apoptosis, thus suppressing tumor growth." (PMID 34642300, 2021). "To validate our STAT1/2 gene expression outlier findings, we used a tumor organoid model." (PMID 34943910, 2021). "As we known, STAT1 is generally recognized as a tumor suppressor gene in cancer cells." (PMID 34178664, 2021). "In other tumor entities, STAT1 is also described as a double-edged sword." (PMID 34638338, 2021). "Signal transducer and activator of transcription 1 enhances anti-tumorigenic immune responses and pro-inflammation function mainly through the induction of cytokines secretion, which in turn leads to an increased amount of anti-tumor immune lymphocytes." (PMID 33834023, 2021). "The expression of JUN, CDK1, IRF1, and STAT1 was significantly higher in the RSI-Low tumours." (PMID 34078917, 2021). "Therefore, it is possible that a hypoxic microenvironment favors lower STAT1 levels in tumor cells that hinder antiproliferative IFN-γ signaling in the tumor cell." (PMID 33807260, 2021). "Mechanistically, CD8+ T cell-derived IFNγ inhibits SLC7A11 expression in cancer cells through activating the transducer and activator of transcription 1 (STAT1), thereby inducing tumor cell ferroptosis and contributes to the anti-tumor efficacy of immunotherapy." (PMID 34796174, 2021). "Moreover, STAT1 is known to have a tumor suppressor role whereas IFIT3 has been shown to play a dual role in cancer." (PMID 34622927, 2021). "miRNAs have regulatory functions: miR-223-3p targets the gene STAT1, involved in interferon-gamma signaling during TB disease; miR-let-7e-5p acts as a tumor suppressor, and its down-regulation may promote the development and progression of carcinomas." (PMID 34804048, 2021). "After TYK2 activation, transcription factors such as signal transducer and activator of transcription 1 (STAT1) and STAT3, are dimerized and activated, thereby promoting the transcription of related genes and causing abnormal tumor cell proliferation and differentiation." (PMID 33731185, 2021). "MiR-155-5p can form a regulatory feedback loop with STAT1 and might trigger cancer immunoediting to allow tumour cells to escape immunosurveillance and even to promote tumourigenesis." (PMID 33902514, 2021). "STAT1 emerges as a tumor suppressor in the early stages of PCa." (PMID 34638338, 2021). "Our data revealed that IL-2 and STAT1 was enriched in tumor cells." (PMID 34026600, 2021). "The consideration of microenvironment for tumor seems essential regarding the expression of a gene as TAP1 as its regulation may be determined by proteins like STAT1 and IRF1." (PMID 34047812, 2021).
tumor (continued). "Oct4 promotes tumor growth, whereas silencing of Stat1 expression reduces tumor growth in vivo." (PMID 34685622, 2021). "Furthermore, depletion of STAT1 in tumor cells disrupts the IFNγ-mediated SLC7A11 suppression and reverses RSL3-induced ferroptosis." (PMID 34796174, 2021). "In our study, the KD gene SPOCK1 was regulated by miR-155-5p, which can form a regulatory feedback loop with STAT1 and might trigger cancer immunoediting to allow tumour cells to escape immunosurveillance and even to promote tumourigenesis." (PMID 33902514, 2021). "We found that the activation of STAT1 displayed the anomalous role of tumor-promoting factors." (PMID 34746227, 2021). "STAT1, the master transcription factor of interferon-related intracellular signaling, has been widely explored in cancer progression and is predominantly considered as a tumor suppressor." (PMID 34462423, 2021). "Therefore, our results indicated that CAR‐T cells induced apoptosis in haematologic tumour cells through IFN‐γ/STAT1 pathway and granzyme B/ perforin/caspase cascades." (PMID 33225580, 2021). "Additionally, JAK2-STAT1 pathway activation, especially increase STAT1 phosphorylation at Y701 has been proposed to be a potential biomarker for anticancer immunotherapy within the tumor." (PMID 34307367, 2021). "In addition, both the FFPE and fresh frozen tumor analysis revealed overexpression of STAT1 and STAT2, even though two different platforms and two separate reference compendia have been used in the analyses." (PMID 34943910, 2021). "STAT1 inhibition was reported in diverse tumor types, along with overexpressed STAT340." (PMID 33846436, 2021). "However, extrapolating from its function in other contexts, it is likely upregulating a T cell-mediated anti-tumor response through the JAK1/STAT1 pathway." (PMID 34122442, 2021). "Similar to our results, therapeutic modulation of myeloid polarization through the IFN-γR/STAT1 signaling axis was found to enhance antitumor immune function by activating tumor infiltrating myeloid cells, regulating PD-L1 expression, and promoting immunogenic cell death." (PMID 33499163, 2021). "Additionally, IFN-γ can directly induce apoptosis or cytostatic behavior in tumor cells, therefore, tumors often downregulate or mutate proteins involved in the IFN-γ signaling cascade, including IFN-γ receptors, STAT1, and JAK1/2." (PMID 34322780, 2021). "Some clinical studies reported that STAT1 apply tumor promoter effects." (PMID 32597160, 2020). "Similarly, in the context of cancer, activation of STAT1 and its target genes are viewed as a tumor suppressive." (PMID 31992798, 2020). "Indeed, PTPN2 deletion in B16 tumor cells enhanced IFNγ signaling, caused a strong change in the expression profile of IFNγ response gene, and increased phosphorylation of STAT1, thereby reducing tumor growth of PTPN2-null mice." (PMID 33003469, 2020). "Significantly, we noted that STAT1 is overexpressed by the MSI-H tumor cells." (PMID 32641473, 2020). "Indeed, we found that the administration of IFNγ resulted in STAT1 phosphorylation and directly increased tumor PD-L1 expression." (PMID 32079180, 2020). "STAT1–EGFR-dependent constitutive phosphorylation is responsible for a positive feedback loop that causes its own overexpression and consequently an increased proliferation of the tumor cells." (PMID 32642677, 2020). "One of the ways of the individual's immune response to tumor antigens is to recruit cytotoxic T cells to secrete interferon-γ (IFN-γ) in the tumor microenvironment through induction of the JAK/STAT1/interferon regulatory factor-1 (IRF-1) pathway, thus inducing PD-L1 expression." (PMID 32884946, 2020). "Indeed, tumor-cells enriched from the ascites of EOC patients displayed constitutively tyrosine-phosphorylated forms of STAT1 and STAT3, and also constitutive GBP1 expression." (PMID 32093058, 2020). "STAT1 is involved in the regulation of immune system and in the process of tumor formation." (PMID 32991625, 2020).
tumor (continued). "CNOT7 expression was increased, whereas STAT1 expression was decreased in HCC tumor tissues." (PMID 32160402, 2020). "For example, STAT1 overexpression in MSI tumor cells may have induced PD-L1 overexpression, which results in an immunosuppressive microenvironment." (PMID 32275681, 2020). "To investigate whether NK cell-mediated tumor surveillance is affected by a switch in STAT1 splicing, we made use of knock-in mice expressing either only the STAT1α (Stat1α/α) or the STAT1β (Stat1β/β) isoform." (PMID 33042133, 2020). "Overall, our findings imply that STAT1-induced upregulation of KTN1-AS1 display tumor-promotive roles in NSCLC progression via regulating miR-23b/DEPDC1 axis, suggesting that KTN1-AS1 may be a novel biomarker and therapeutic target for NSCLC patients." (PMID 32396871, 2020). "Consistent with this concept, PLSCR1 expression resulted in increased CSC properties by promoting transactivation of STAT1 in BLBC, implying the critical role of PLSCR1 in controlling the viability of CSCs, which are implicated in mediating tumor initiation and metastasis 39-41." (PMID 32292520, 2020). "Thus, when RELA and STAT1 were up-regulated in a tumor, parallel to doxycycline added in vitro, the genetic circuit was then switched on." (PMID 32712598, 2020). "The increased serum IL-6 activated STAT3/c-MYC signaling in peripheral monocytes, enhanced the transcription of miR-25–3 p, suppressed PTPRO expression, promoted PD-L1 through both JAK2/STAT3/c-MYC and JAK2/STAT1 signaling, and promoted tumor growth by enhancing T-cell exhaustion." (PMID 32581055, 2020). "Together with our data, this indicates that the C-terminal TAD of STAT1 has a dual role in NK cells: it is required for full-fledged STAT1 expression and anti-tumor activity but it is also targeted by negative regulatory circuits that control NK cell cytotoxicity through its S727 phosphorylation." (PMID 33042133, 2020). "Previously, STAT1 had frequently reported to display functional effects on various tumor progression, and its overexpression could also activate the transcription of some lncRNAs in several tumors." (PMID 32396871, 2020). "pY-STAT1 was undetectable in tumor cells of Stat1∆IECApcMin tumors but appeared upregulated in the stroma similar to upregulation of total STAT1." (PMID 32444775, 2020). "The TF–target gene network analysis uncovered an unexpected scenario where both correlation-enhancing genes (with higher correlation in the tumor) and -repressing genes (with lower correlation in the tumor) were targeted by STAT1 (6A), STAT3 (6B), KDM1A (6C), PML and RELA." (PMID 33384992, 2020). "Moreover, the results of immunoblotting showed that the tumor PD-L1 protein level was highly increased, and the phosphorylation of STAT1 and its downstream transcription factor IRF1 was significantly increased in the resected tumors from the DAC and OXP group." (PMID 32079180, 2020). "Furthermore, Stat1, a protein with both tumor suppressor and oncogenic properties was bound and activated by CTCFL." (PMID 32393311, 2020). "CNOT7 and STAT1 expression levels in tumor and normal liver tissues." (PMID 32160402, 2020). "Furthermore, the NPM-ALK complex eventually inhibits IFN-γ-mediated STAT1 pathway-induced suppression of tumor growth." (PMID 31952344, 2020). "Moreover, qPCR indicated that the levels of STAT1 were remarkably up-regulated in 127 NSCLC tumor samples." (PMID 32396871, 2020). "Besides, the STAT1 levels were also up-regulated across stage I to IV of NSCLC tumor samples using UALCAN program analysis." (PMID 32396871, 2020). "STAT1 usually acts as the transcriptional factor in the tumor immune function." (PMID 32891166, 2020). "Mutation of S727 to alanine (STAT1-S727A) has no impact on NK cell maturation but increases NK cell cytotoxicity and NK cell-dependent tumor growth control." (PMID 33042133, 2020).